PVT1 (Pvt1 oncogene)
Diseases named in the same sentence as PVT1 in open-access papers (continued):
Sharing a sentence is not in itself a finding about the gene and the disease.
cancer (continued). "Analyzing the interplay, we have zeroed in on E2F1, FOXM1 (transcription factors) and PVT1 (lncRNA) regulatory path as recurring pan-cancer regulatory entity." (PMID 30809433, 2019). "PVT1 can act as a “sponge” for miRNAs to inhibit their activities, thereby affecting proliferation, invasion, and angiogenesis of cancer." (PMID 31380270, 2019). "PVT1 siRNA silencing inhibited the proliferation of cancer cells and reduced the expression of TGF-β1, while PVT1 overexpression played an opposite role." (PMID 29760583, 2018). "PVT1 shows very low expression in most normal human tissues, but is highly expressed in many malignant tumors and tumor cell lines." (PMID 29445147, 2018). "Our work not only confirms the frequent amplification of PVT1 in cancer, but it also reveals that PVT1 amplifications can be focal." (PMID 30217017, 2018). "Driver lncRNA PVT1 was amplified in 18.8% of pan cancers, and gain of PVT1 was required for by stabilizing MYC protein." (PMID 30216655, 2018). "This distribution of selected mutations over a 2Mb region concurs with the recent finding that copy number gains of the entire segment, incorporating Myc, Pvt1, and the Gsdmc family locus, is required to give acceleration of cancer in mouse models." (PMID 29985390, 2018). "PVT1 represents a non‐protein coding locus that is co‐overexpressed with the myc proto‐oncogene, indicating its role in cancer biology." (PMID 30341811, 2018). "PVT1 mediates increased cell proliferation, decreased apoptosis and chemotherapy resistance in these cancers." (PMID 30046623, 2018). "First, we validated 3 well-known lncRNAs (H19, HULC, and PVT1), which have been reported to be involved in a variety of cancers." (PMID 30305026, 2018). "The discovery of cancer-associated lncRNAs such as HOTAIR, MALAT1, and PVT1 uncovered an important role for lncRNAs in oncogenesis." (PMID 30217017, 2018). "LncRNA PVT1 plays a role as oncogene in the development of various types of malignant tumors and shows abnormally upregulated expression." (PMID 29760583, 2018). "Abnormal expression of PVT1 in cancerous tissue has confirmed it as an important player in tumorigenesis of cancers." (PMID 29088881, 2017). "Tseng60 indicated that high MYC protein levels in 8q24-amplified human cancer cells require gain of PVT1 expression to suppress phosphorylation of T58, in turn protecting MYC protein from degradation." (PMID 28389669, 2017). "Plasmacytoma variant translocation 1 (PVT1), a long intergenic non-coding RNA encoded by the human oncogene PVT1, is located adjacent to the MYC locus on the well-known cancer-related region 8q24." (PMID 29348896, 2017). "Four studies with 220 patients and 215 health controls showed data for circulating PVT1 on cancer detection/diagnosis." (PMID 29088881, 2017). "A total of 15 studies including 1711 patients were recruited to assess the effect of PVT1 expression on OS in various cancers." (PMID 29348896, 2017). "lncRNA PVT1 has been found to be up‐regulated in several cancers, and overexpressed PVT1 exerts oncogenic function by promoting cancer cells proliferation, invasion, and metastasis." (PMID 29047230, 2017). "PVT1 has been demonstrated as an oncogenic lncRNA that is usually upregulated in cancer tissues compared with normal tissues." (PMID 29244840, 2017). "EdU incorporation assay also validated PVT1 upregulation promoted cancer cell proliferation significantly in statistics." (PMID 29156724, 2017). "Compared to corresponding normal tissues, PVT1 expression was significantly upregulated in 18 types of cancer and further being an effective diagnosis biomarker in 16 of them." (PMID 29088881, 2017). "Our results suggested that elevated PVT1 expression predicted a poor clinical outcome for overall survival in nine types of cancers (HR = 1.40, 95% CI: 1.21–1.59)." (PMID 29348896, 2017). "PVT1 has been reported to be upregulated in a variety of cancers, and plays an important role in cancer progression." (PMID 29348896, 2017).
cancer (continued). "PVT1 is increased in the NSCLC patients, and the high expression of PVT1 was related with the poor prognostic outcome of cancer patients." (PMID 27992369, 2017). "This study aimed to reanalyze and determine the effect of PVT1 on cancer diagnosis, especially detection in serum." (PMID 29088881, 2017). "Here, we conducted a meta-analysis to investigate the prognostic value of PVT1 expression in cancers." (PMID 29348896, 2017). "Given lncRNA PVT1 for an example, users can rapidly find that PVT1 is frequently amplified in 15 cancer types when selecting the TCGA data cohort through the “lncRNA” module." (PMID 29657279, 2017). "The results showed that elevated PVT1 expression predicted a poor outcome for overall survival (OS) in nine types of cancers (HR = 1.40, 95% CI: 1.21–1.59)." (PMID 29348896, 2017). "Since MYC protein is refractory to small-molecule inhibition, the dependence of high MYC protein levels on PVT1 lncRNA suggests a promising way to therapeutically target this protein in MYC-positive cancers." (PMID 29165379, 2017). "Especially, PVT1, regarded as one of the most familiar oncogenic lncRNAs, exhibited the ability to improve the development and progression of different cancers." (PMID 29348896, 2017). "How this tight balance between pro-survival during DNA repair and apoptosis/cell death is disrupted in cancer will require further research in the downstream targets of the PVT1 locus transcripts." (PMID 29113413, 2017). "Basing on TCGA RNA-Seq data, the expression of PVT1 was suggested being a possible biomarker to distinguish cancer from normal tissue." (PMID 29088881, 2017). "The mechanisms of PVT1 dysregulation in these cancers are quite complex and far from being fully understood." (PMID 29244840, 2017). "Similar to the performance in tissues, the pooled–AUC of circulating PVT1 was still more than 0.80 with DOR being 13.86, which indicated that it was feasible to detect cancer by usingcirculating PVT1." (PMID 29088881, 2017). "A systematic search was performed through the PubMed, EMBASE, Web of Science, Ovid and Cochrane library databases for eligible studies on prognostic value of PVT1 in cancers from inception up to June, 2017." (PMID 29348896, 2017). "Differential expression of PVT1 between cancers and corresponding normal tissues and receiver operating characteristic (ROC) curve were analyzed for all types of cancers in TCGA database." (PMID 29088881, 2017). "The last years have been the scene of increasing advancements in studying PVT1 role in tumour cells and its overexpression appears as a frequent event in a wide variety of cancers." (PMID 28187158, 2017). "It all suggested that PVT1 expression, especially in serum, was a higher effective biomarker for human cancer detection." (PMID 29088881, 2017). "Two studies including 234 cancer patients reported the HRs for PFS, and the results found that upregulation of PVT1 expression was associated with poor PFS (HR = 1.63, 95% CI: 1.34–1.93)." (PMID 29348896, 2017). "In recent years, numerous studies have demonstrated that high PVT1 expression significantly correlated with poor prognosis of patients with nearly all types of cancers." (PMID 29348896, 2017). "The transcript levels of PVT1 were significantly up-regulated (cancer/normal > 2.0) in 78.8% (82 of 104) of ESCC cancer tissues, with the mean fold-change of 2.92 in tumor tissues compared with that in their normal counterparts." (PMID 28404954, 2017). "In this study, we found that expression of PVT1 was significantly up-regulated in ESCC cancer tissues and cell lines and predicts poor prognosis of ESCC patients." (PMID 28404954, 2017). "Meanwhile, the sensitivity of 0.83 (95% CI: 0.76–0.89) and the specificity of 0.74 (95% CI: 0.70–0.84) approved circulating PVT1 had a relatively high accuracy in human cancer detection." (PMID 29088881, 2017).
cancer (continued). "Pvt1, for example, has been identified as a candidate oncogene in humans, the overexpression of this gene was correlated with cancers of the breast, colorectum, ovary, and even hematological malignancies." (PMID 29383134, 2017). "More importantly, PVT1 expression has been significantly correlated with clinical features such as recurrence and survival in various cancers." (PMID 29046366, 2017). "Overexpression of PVT1 was detected in ESCC cancer cell lines compared with that in the immortalized esophageal epithelium cell lines (NE1)." (PMID 28404954, 2017). "This meta-analysis is the first to demonstrate that high expression of the long noncoding RNA PVT1 is related to cancer detection." (PMID 29088881, 2017). "Several previous studies also observed the promising prognostic value of PVT1 in multiple types of cancer." (PMID 29244840, 2017). "When users continue to select other data cohorts, such as the progenetix dataset, PVT1 shows amplification in more than 10% of samples within individual tumors across 33 cancer types." (PMID 29657279, 2017). "Some meta-analyses focused on the association of lncRNAs such as MALAT-1, AFAP1-AS1, H19, and PVT1 and metastasis as well as prognosis with cancer; all analyzed only the lncRNAs detected in cancer tissues." (PMID 28146578, 2017). "In our study, we found that expression of PVT1 was significantly up-regulated in the ESCC cancer tissues than that in the normal counterparts and exerted oncogenic roles in ESCC." (PMID 28404954, 2017). "This current study aimed to analyze the differential expression of PVT1 in different types of common cancers and assess the effect of PVT1 expression on cancer diagnosis/detection." (PMID 29088881, 2017). "For example, lncRNA PVT1 were reported to be dysregulated and likely played important roles in a variety of cancers." (PMID 28938549, 2017). "Recent findings revealed that gain of PVT1 expression was required for high MYC protein levels in human cancer cells." (PMID 27366943, 2016). "When all cancers were considered, more than 18% of them presented the duplication of both pvt1 and myc, whereas fewer than 0.5% showed only myc or pvt1 duplicated." (PMID 26992233, 2016). "Some well-known cancer-associated lncRNAs, such as H19, XIST, HOTAIR, MALAT1, MEG3, HNF1A-AS1 and PVT1, have indicated oncogenic and/or tumor suppressive roles like protein-coding genes in various cancers." (PMID 27074572, 2016). "For example, PVT1, a lncRNA that was consistently amplified and expressed in four different cancer types, is located at the chromosome site 8q24." (PMID 27147563, 2016). "In general, PVT1 locus amplification contributed significantly for PVT1 misregulation in most cancer types." (PMID 27366943, 2016). "The 8q24 region of the human genome, which contains MYC and PVT1, is one of the most common sites of cancer-related amplifications." (PMID 27232880, 2016). "Although all cancers showed alterations in PVT1 promoter methylation, significant levels of promoter hypomethylation were found in KIRC." (PMID 27366943, 2016). "We found that patients with high PVT1 expression levels also showed a significant increase of MYC protein concentration for five cancers, including KIRC." (PMID 27366943, 2016). "For example, the lncRNAs LOC100128593 and PGM5-AS1 showed the most pervasive down-regulation in 13 cancer types; several well-characterized lncRNAs such as HOTAIR, H19 and PVT1, also showed dysregulation in at least nine different cancer types." (PMID 27147563, 2016).
cancer (continued). "One interesting example was a cancer associated lncRNA PVT1, which was in the top 10% of hubs in the KICH cancer ceRNA network." (PMID 27580177, 2016). "The oncogenic effects of PVT1 have been further highlighted by more recent studies demonstrating its overexpression and amplification in multiple cancer types." (PMID 27232880, 2016). "PVT1 encodes a long noncoding RNA that is often amplified and upregulated along with MYC across multiple cancers." (PMID 27579533, 2016). "A thorough analysis of individual profiles detected that PVT1 locus amplification is observed in 40% of the patients from 13 cancers that have PVT1 up-regulation." (PMID 27366943, 2016). "Recent studies have reported that PVT1 functions as an oncogene and accelerates the progression of cancers." (PMID 27588491, 2016). "The non-coding Pvt1 gene neighboring Myc that harbors a SE was recently shown to contribute to high expression of this locus in cancer cells." (PMID 26546038, 2015). "This oncogenic attitude of PVT1 gained support from later evidences of frequent upregulation and amplification in a wide variety of cancers." (PMID 25883951, 2015). "Overexpression of PVT1 is a powerful predictor of tumor progression and patient survival in a diverse range of cancer types." (PMID 25624916, 2015). "Compared with normal counterparts, the PVT1 expression was upregulated significantly in 62.5% (20 of 32) of cancer tissues (P < 0.01)." (PMID 26517688, 2015). "Despite some advancements in modelling the PVT1 role in cancer, there are many questions that remain unanswered concerning the precise molecular mechanisms underlying its functioning." (PMID 25883951, 2015). "Overall, the expression levels of PVT1 appear to be higher (up to 100 times) in cancer cell lines than in human primary cells and tissues." (PMID 25883951, 2015). "Gain of single supernumerary segment encompassing Myc, Pvt1, Ccdc26 and Gsdmc has shown to promote cancer." (PMID 25885205, 2015). "In terms of topological properties, PVT1 switches from being the first of the hubs in the normal-MMI-network to fall outside the list of nodes of the cancer network." (PMID 25033876, 2014). "the PVT1 neighborhood in the normal-MMI-network encompasses cancer related genes as well as genes involved in mammary gland development and cell morphogenesis; and ii." (PMID 25033876, 2014). "PVT1 role in cancer seems to be that of an inhibitor of apoptosis, so this is another potential target gene that is worth consideration." (PMID 21436996, 2011). "Also, PVT1 modulates transcription factors known to have oncogenic roles in cancer, which increases breast tumorigenicity." (PMID 41459628, 2026). "PVT1 expression significantly increases in cancer of the breast patients' cell lines and plasma." (PMID 41459628, 2026). "Plasmacytoma variant translocation 1 (PVT1) is a long noncoding gene located on the 8q24 chromosomal locus and is involved in a variety of cancer-related processes including activating growth signaling pathways, stimulating angiogenesis, and promoting stem-cell signaling pathways." (PMID 40024473, 2025). "We speculated that, as previously observed in different cancer models, PVT1 binds to and carries PRC2 complex to target genomic regions to suppress transcription of specific genes." (PMID 39922814, 2025). "Indeed, although PVT1 has been functionally studied and demonstrated to act as a pan-oncogene in several cancer models, including BC, its direct and nuclear functional association with ERα and the estrogenic signaling has not been investigated so far." (PMID 39922814, 2025).
cancer (continued). "The abundance of transcripts from 5’-PVT1 in cancer cells suggested that 5’-PVT1 might play a crucial oncogenic role in these cell lines." (PMID 40027648, 2025). "CENP-H can promote cancer growth and metastasis through PI3K/AKT, survivin, and mitochondrial apoptosis signaling mechanisms, and it can be regulated by long non-coding ribonucleic acid (lncRNA) plasmacytoma variant translocation 1 (PVT1)/miR-612, Sp1, or Sp3." (PMID 40071086, 2025). "Pvt1 has been shown in both developmental and cancer contexts to promote proliferation." (PMID 41223055, 2025). "Although PVT1 itself is regarded as a potent oncogene in cancer, the function of its fusions in carcinogenesis remains unclear." (PMID 38919532, 2024). "Thus, there is exciting potential for using the Pvt1 locus as a therapeutic handle to modulating Myc levels in cancer." (PMID 39195572, 2024). "In this review, we detected that PVT1 lncRNA forms a great variety of fusions with other lncRNAs and mRNAs in different types of cancer, but their functions are still unknown." (PMID 38292185, 2024). "PVT1 is also an lncRNA with an oncogenic role in many malignant tumors." (PMID 38559560, 2024). "By considering that PVT1 was recently reported to be a enhancer of chemosensitivity in cancer cells, we used several agents with different mechanisms of action: direct DNA damage (carboplatin), DNA synthesis inhibition (5‐FU) or cell division disruption (paclitaxel)." (PMID 38098223, 2024). "Also, an analysis of the TCGA database confirmed this observation as over 97% of MYC-upregulated cancers had coincreased PVT1 copy numbers." (PMID 38731892, 2024). "Furthermore, several mutations at the PVT1 promoter region (obtained by published cancer human genomes), collectively highlight the importance of an intact PVT1 locus for MYC upregulation and cancer progression." (PMID 39123456, 2024). "AA patients had elevated plasma levels of MALAT1 and PVT1 compared with cancer-free smokers." (PMID 38791954, 2024). "It has been demonstrated that PVT1 is important for multiple types of cancer progression." (PMID 39376555, 2024). "To demonstrate BioPathNet’s ability to uncover novel lncRNA regulations, we focused on the lncRNA PVT1, a Myc regulator frequently over-expressed in cancers, crucial for tumor initiation, proliferation, invasion, and apoptosis, and linked to poor prognosis and therapy resistance." (PMID 39372928, 2024). "The PVT1-MYC duet, which has been implicated in the regulation of cell growth and survival in various cancers, may represent another layer of complexity in PDAC biology, potentially offering novel insights into disease progression and therapeutic intervention." (PMID 39376555, 2024). "The authors detected that Pvt1 was overexpressed in G-MDSCs derived from cancer samples." (PMID 36817434, 2023). "The amplification and translocation of the 8q24 region may be responsible for the upregulation of PVT1 in a variety of cancers." (PMID 36624401, 2023). "PVT1 is an oncogenic lncRNA which has a critical role in cancer development and pathophysiology." (PMID 36624401, 2023). "We also performed rescue assays to evaluate whether miR-375 is necessary for PVT1-regulated cancer stemness and immune evasion." (PMID 36894542, 2023). "Several lncRNAs, such as MALAT1, HOTAIR, PVT1, NEAT1, ANRIL, and SPRY4-IT1, have recently been identified, particularly in cell lines, liquid biopsy, and tissue biopsy samples and have been associated with cancer pathogenesis." (PMID 37424727, 2023). "MYC and PVT1 belong to the 8q24 genomic region, which is frequently altered in cancer." (PMID 36901971, 2023). "Also, targeting downstream modulators of NK-1R activity to fight cancer cells, as it is the case of long non-coding RNA PVT1, should be considered." (PMID 37958914, 2023).